TRIM49 (tripartite motif containing 49)
Synonyms: RNF18; TRIM49A; TRIM49L2
Tractability: No criterion of Open Targets' tractability assessment is met for any kind of drug.
Gene: Protein-coding gene on chromosome 11 (89,797,655 to 89,808,575, reverse strand). Ensembl gene ENSG00000168930.
Gene Ontology:
Molecular function: protein binding; protein kinase binding; ubiquitin protein ligase activity; zinc ion binding
Biological process: innate immune response; regulation of gene expression
Cellular component: cytoplasm
Genetic constraint (gnomAD): Loss-of-function variants: 4 observed, 9.45 expected, observed/expected ratio (o/e) 0.42, 90% interval 0.21 to 0.97. That is too few expected variants to judge how well the gene tolerates losing a copy. Missense variants: 166 observed, 274.41 expected, observed/expected ratio (o/e) 0.6, 90% interval 0.53 to 0.69. Synonymous variants: 64 observed, 87.25 expected, observed/expected ratio (o/e) 0.73, 90% interval 0.6 to 0.9.
Homologues: Paralogues in human: TRIM49C (99% identical), TRIM49B (95% identical), TRIM49D1 (85% identical), TRIM49D2 (85% identical), TRIM51 (75% identical), TRIM51G (71% identical), TRIM43 (52% identical), TRIM43B (51% identical), TRIM64 (46% identical), TRIM64B (46% identical), TRIM64C (45% identical), TRIM77 (43% identical), and 68 more.
Diseases named in the same sentence as TRIM49 in open-access papers:
TRIM49 is named in the same sentence as 8 diseases in open-access papers, as found by Europe PMC text mining. Sharing a sentence is not in itself a finding about the gene and the disease. The quoted sentences say what the papers report.
retinal degeneration (1 paper, 2025). Degeneration of the retina. "TRIM49 deficiency thus defines a novel subcategory of retinal degenerations associated with autophagic defects in the human RPE." (PMID 40956390, 2025).
retinitis pigmentosa (1 paper, 2025). Retinitis pigmentosa (RP) is an inherited retinal dystrophy leading to progressive loss of the photoreceptors and retinal pigment epithelium and resulting in blindness usually after several decades. "Based on next‐generation sequencing data of retinitis pigmentosa (RP) patients and controls, this study identifies TRIM49 as a novel gene for autosomal recessive RP." (PMID 40956390, 2025).
infection (2 papers, 2023 to 2025). The state of being infected such as from the introduction of a foreign agent such as serum, vaccine, antigenic substance or organism. "Western Blot as well as qRT-PCR experiments further confirmed the expression of DUX4 and known DUX4-target genes TRIM48, TRIM49, ZSCAN4, ZSCAN5a, ZSCAN5d and RFPL4A upon HSV-1, HCMV and KSHV-infection 25 in different experimental settings." (PMID 38168299, 2023).
TRIM49 also shares sentences with these, for which no sentence is quoted: breast carcinoma (1 paper); HCMV infection (1); Mendelian diseases (1); neurodegenerative disease (1); osteonecrosis (1).